ZNF365 (zinc finger protein 365)
Description:
May play a role in uric acid excretion. Involved in the regulation of neurogenesis. Negatively regulates neurite outgrowth. Involved in the morphogenesis of basket cells in the somatosensory cortex during embryogenesis. Involved in the positive regulation of oligodendrocyte differentiation during postnatal growth. Involved in dendritic arborization, morphogenesis of spine density dendrite, and establishment of postsynaptic dendrite density in cortical pyramidal neurons (By similarity). Involved in homologous recombination (HR) repair pathway. Required for proper resolution of DNA double-strand breaks (DSBs) by HR. Is required for recovery of stalled replication forks, and directly contributes to genomic stability. Interacts with PARP1 and mediates MRE11-dependent DNA end resection during replication fork recovery. Contributes to genomic stability by preventing telomere dysfunction.
Synonyms: KIAA0844; UAN; Su48; ZNF365D
Tractability: No criterion of Open Targets' tractability assessment is met for any kind of drug.
Gene: Protein-coding gene on chromosome 10 (62,374,192 to 62,480,288, forward strand). Ensembl gene ENSG00000138311.
Subcellular location: Cytoplasm, cytoskeleton, microtubule organizing center, centrosome
Subcellular location (Human Protein Atlas): Centriolar satellite; Centrosome; Vesicles
Gene Ontology:
Molecular function: protein binding
Biological process: negative regulation of neuron projection development; regulation of DNA strand resection involved in replication fork processing; regulation of double-strand break repair via homologous recombination; telomere maintenance; cerebellar molecular layer morphogenesis; dendrite arborization; dendritic spine morphogenesis; positive regulation of oligodendrocyte differentiation; regulation of neuron projection development
Cellular component: centrosome
Genetic constraint (gnomAD): Loss-of-function variants: 22 observed, 36.84 expected, observed/expected ratio (o/e) 0.6, 90% interval 0.43 to 0.85. The upper end of that interval is the gene's LOEUF score, 0.85, which puts it in group 3 of 6, group 1 being the genes least tolerant of losing a copy. Missense variants: 448 observed, 527.18 expected, observed/expected ratio (o/e) 0.85, 90% interval 0.79 to 0.92. Synonymous variants: 188 observed, 204.54 expected, observed/expected ratio (o/e) 0.92, 90% interval 0.81 to 1.04.
Homologues: Orthologues: chimpanzee ZNF365 (99% identical), macaque ZNF365 (98% identical), rabbit ZNF365 (92% identical), pig ZNF365 (91% identical), guinea pig ZNF365 (90% identical), dog ZNF365 (89% identical), rat Zfp365 (86% identical), mouse Zfp365 (85% identical), tropical clawed frog znf365 (50% identical), zebrafish znf365 (27% identical). Paralogues in human: FBXO41 (29% identical).
Diseases named in the same sentence as ZNF365 in open-access papers:
ZNF365 is named in the same sentence as 41 diseases in open-access papers, as found by Europe PMC text mining. Sharing a sentence is not in itself a finding about the gene and the disease. The quoted sentences say what the papers report.
breast carcinoma (21 papers, 2010 to 2024). "The study found that one locus (rs1432679, p=0.043) in the EBF1 gene, another one (rs10759243, p =0.012) in the KLF4-RPL36AP6 gene, and yet another (rs10822013, p =0.046) in ZNF365 gene were association with breast cancer based on χ2 tests." (PMID 27863437, 2016). "In a recent meta-analysis including five genome-wide association studies, a variant (rs10995190) in the ZNF365 gene, which promotes genome stability during DNA damage, was associated with both breast cancer risk and mammographic density." (PMID 25522654, 2014). "A nearby SNP in ZNF365 was also associated with breast cancer risk in a study of unselected cases and in a study of mammographic density." (PMID 23544012, 2013). "Two other loci, in ZNF365 (rs16917302) on 10q21 and a locus on 20q13 (rs311499), were also associated with breast cancer risk in BRCA2 mutation carriers with P-values<10−4 (P = 3.8×10−5 and 6.6×10−5, respectively)." (PMID 23544012, 2013). "ZNF365 has been implicated in breast cancer and Crohn’s disease and a role in heart disease has not been reported." (PMID 23593153, 2013). "The minor allele of rs10995190 in ZNF365 was associated with a reduced risk of breast cancer, where each copy of allele "A" was estimated to confer a HR of 0.90 (95% CI: 0.82 to 0.98, P-trend = 0.015)." (PMID 22348646, 2012). "A different SNP (rs16917302) in ZNF365, which is only weakly correlated with rs10995190 (pairwise r2 is approximately 0.10 in the present sample) was previously identified via a GWAS of breast cancer in BRCA2 mutation carriers." (PMID 22348646, 2012). "A third SNP previously associated with breast cancer, rs10995190 in ZNF365, shows a possible association with breast size; in addition, we find a second SNP in the same gene (rs7089814) that is significantly associated with breast size." (PMID 22747683, 2012). "The chromosome 10 locus was in ZNF365, which contains another variant that has recently been associated with breast cancer in an independent study of unselected cases." (PMID 21060860, 2010). "For one of the novel SNPs identified in the discovery GWAS, ZNF365 rs16917302, there was weak evidence of association with breast cancer risk (P = 0.01); however, an uncorrelated SNP, rs17221319 (r2<0.01), 54 kb upstream of rs16917302 had stronger evidence of association (P = 6×10−3)." (PMID 23544012, 2013). "Previously reported BRCA2-modifying alleles for breast cancer, including those in FGFR2, TOX3, MAP3K1, LSP1, 2q35, SLC4A7, 5p12, 1p11.2, ZNF365, and 19p13.1 (ER-negative only), are also associated with breast cancer risk in the general population and/or BRCA1 mutation carriers." (PMID 23544012, 2013). "We found that SNP rs10995190 ZNF365 is associated with BRCA2 breast cancer risk." (PMID 22348646, 2012). "A recent multistage GWAS of 15,992 sporadic breast cancer cases and 16,891 controls also observed an inverse association (per allele OR = 0.82, 95% CI 0.82–0.91, ) between breast cancer risk and rs10509168, a SNP 18kb from rs16917302 (pairwise ) and located in intron 4 of ZNF365." (PMID 21060860, 2010). "However, the ZNF365 locus has recently independently been associated with breast cancer risk in sporadic tumors, highlighting the potential significance of this zinc finger-containing gene in breast cancer pathogenesis." (PMID 21060860, 2010). "The ZNF365, ESR1, LSP1 and SGSM3 loci are also associated with breast cancer risk, implicating a shared genetic basis of mammographic density and breast cancer." (PMID 26275715, 2015). "However, when taking tumor subtypes into account, associations were also observed for ER− breast cancer (MERIT40) and 2q35 and ZNF365 (ER+ breast cancer)." (PMID 27814745, 2016).
breast carcinoma (continued). "Recent genome-wide association studies of breast cancer have identified eight additional breast cancer susceptibility loci: rs1011970 (9p21, CDKN2A/B), rs10995190 (ZNF365), rs704010 (ZMIZ1), rs2380205 (10p15), rs614367 (11q13), rs1292011 (12q24), rs10771399 (12p11 near PTHLH) and rs865686 (9q31.2)." (PMID 22348646, 2012). "Interestingly, three genes in our list (ZNF365, SGSM3, and LSP1) were significantly annotated (using Webgestalt and Disgenet) with the “category mammographic density”, that is a strong risk factor for breast cancer." (PMID 28569218, 2017). "The local genetic correlation analysis in our study highlighted specific loci at which MD phenotypes and breast cancer showed evidence of shared heritability (DA: ESR1, ZNF365, LSP1, and MKL1; NDA: 8p11.23; PMD: ESR1 and ZNF365)." (PMID 35414113, 2022).
Crohn disease (4 papers, 2013 to 2023). A gastrointestinal disorder characterized by chronic inflammation involving all layers of the intestinal wall, noncaseating granulomas affecting the intestinal wall and regional lymph nodes, and transmural fibrosis. "For main effects, JAK2, TNFSF15, ZNF365 and PTPN22 showed consistent small P‐values in the original sequencing data as well as the validation with IBD and Crohn's disease data sets." (PMID 29441677, 2018).
narcolepsy (4 papers, 2017 to 2024). A sleep disorder characterized by a tendency for excessive sleepiness during the day which occurs even after adequate sleep in the nighttime. "IL10RB–IFNAR1 (the IL-10 and interferon receptor gene region), ZNF365 (that encodes the transcription factor ZNF365), and P2RY11 (encodes P2Y purinoceptor 11) and the chemokine receptor CCR1–CCR3 region are all linked to narcolepsy." (PMID 36358399, 2022). "Located within the gene, the functions PPP2R2C, GPM6A, EPHX2, NKAIN3, ZNF365, TENM4, and PR2Y11 are related to narcolepsy." (PMID 32358372, 2020).
schizophrenia (3 papers, 2011 to 2019). A major psychotic disorder characterized by abnormalities in the perception or expression of reality. "Furthermore, a subunit for GABA receptor 1B (GABBR1), DTW Domain Containing 2 (DTWD2), and DISC1-Binding Zinc-Finger Protein (ZNF365), have been associated with multiple often comorbid disorders, including addiction, bipolar disorder, and schizophrenia." (PMID 31040859, 2019).
autoimmune disease (2 papers, 2023 to 2024). A disorder resulting from loss of function or tissue destruction of an organ or multiple organs, arising from humoral or cellular immune responses of the individual to their own tissue constituents. "Almost all variants identified (ZNF365, TNFSF4, NAB1, IKZF4-ERBB3, CTSC, DENND1B, SIRPG, and PRF1) are the same or strongly linked with markers associated with other autoimmune diseases." (PMID 37188663, 2023).
cervical cancer (1 paper, 2017). A primary or metastatic malignant neoplasm involving the cervix. "In the Human Protein Atlas, OVOL1 and PRDM1 showed low, ENO1 medium, while ZNF365 showed no protein expression in cervical cancer." (PMID 28670312, 2017).
colonic disease (1 paper, 2017). "In particular, carriers of at least one NOD2 mutations [P = 2.1e-7, OR 2.9 (1.9–4.3)], were at risk for the colonic disease, as well as the carriers of mutations in rs10761659 (ZNF365) [P = 6.6e-4, OR 2.1 (1.4–3.1)] and those in rs10000113 (IRGM) [P = 2.8e-4, OR 2.0 (1.4–3.0)]." (PMID 28052082, 2017).
Ewing sarcoma (1 paper, 2018). A small round cell tumor that lacks morphologic, immunohistochemical, and electron microscopic evidence of neuroectodermal differentiation. "The 10q21 variants strongly associated with Ewing's sarcoma are located in a block containing four genes: ADO (encoding cysteamine dioxygenase), ZNF365 (encoding zinc-finger protein 365), EGR2 (encoding early growth response protein 2) and LOC107984012 (unknown function)." (PMID 29719630, 2018).
hyperuricemia (1 paper, 2017). An abnormally high level of uric acid. "The functional relevance of these genes with uric acid involvement is largely unknown, except that the emergence of ZNF365 variants is correlated with disappearance of uricase in primate evolution and hence causing a predisposition to hyperuricemia in humans." (PMID 28095793, 2017).
invasive breast carcinoma (1 paper, 2016). A carcinoma that infiltrates the breast parenchyma. "We have also shown for the first time that seven of the known invasive breast cancer predisposition loci not previously shown to be associated with DCIS have comparable ORs for IDC and DCIS: rs4973768 (SLC4A7), rs3821902 (ATXN7), rs10995190 (ZNF365), rs554219 (CCND1), rs3757318 and rs2046210 (ESR1)." (PMID 26884359, 2016).
lung fibrosis (1 paper, 2022). "Our findings demonstrate that ZNF365 is upregulated in IPF and experimental lung fibrosis and suggest a protective role since its absence increases experimental lung fibrosis mechanistically associated with the induction of cell senescence." (PMID 36139424, 2022). "In summary, we have discovered that ZNF365 is upregulated in hyperplastic alveolar epithelial cells and fibroblast foci in IPF lung, as well as in a mice experimental pulmonary fibrosis model, likely as a defense mechanism." (PMID 36139424, 2022).
Uric acid nephrolithiasis (1 paper, 2017). The presence of uric acid-containing calculi (stones) in the kidneys. "Moreover, strong association of UACl with ZNF446 itself is interesting because studies have shown association of ZNF365, on chromosome 10, with urolithiasis in children, and with uric acid nephrolithiasis in adults." (PMID 28095793, 2017).
uveitis (1 paper, 2021). An inflammatory process affecting a part of or the entire uvea. "Genome-wide association studies (GWASs) have provided a powerful tool for the genome-wide analysis of genetic susceptibility to uveitis, revealing several genes associated with uveitis, including IL23R/C1ORF141, STAT4, and ADO/ZNF365/Egr2." (PMID 34869347, 2021).
cancer (2 papers, 2015 to 2019). A tumor composed of atypical neoplastic, often pleomorphic cells that invade other tissues. "For example, PCSK6, a pro-protein convertase, plays an important role in cancer cell proliferation and ZNF365, a DNA repair pathway gene in the homologous recombination (HR) pathway." (PMID 31681618, 2019).
ZNF365 also shares sentences with these, for which no sentence is quoted: psychiatric diseases (3 papers); tumor (3); atopic dermatitis (2); psoriasis (2); allergic disease (1); alopecia areata (1); ankylosing spondylitis (1); asthma (1); bipolar disorder (1); developmental verbal dyspraxia (1); eczema (1); epilepsy (1); heart disease (1); inflammatory bowel disease (1); metabolic syndrome (1); neurological disorders (1); ovarian carcinoma (1); primary biliary cholangitis (1); primary sclerosing cholangitis (1); rheumatoid arthritis (1); sarcoma (1); Temple syndrome (1); ulcerative colitis (1); urolithiasis (1); vitiligo (1); VKH disease (1); Williams syndrome (1).